CDC37 (cell division cycle 37, HSP90 cochaperone)
Description:
Co-chaperone that binds to numerous kinases and promotes their interaction with the Hsp90 complex, resulting in stabilization and promotion of their activity. Inhibits HSP90AA1 ATPase activity.
Synonyms: P50CDC37
Tractability: Small molecule: a structure with a bound ligand is known. PROTAC: UniProt records ubiquitination sites on it; ubiquitination databases record sites on it; its protein half-life has been measured; a small molecule that binds it is known.
Gene: Protein-coding gene on chromosome 19 (10,391,090 to 10,420,185, reverse strand). Ensembl gene ENSG00000105401.
Subcellular location: Cytoplasm
Subcellular location (Human Protein Atlas): Cytosol
Pathways (Reactome):
Disease: Constitutive Signaling by EGFRvIII; Constitutive Signaling by Ligand-Responsive EGFR Cancer Variants; Constitutive Signaling by Overexpressed ERBB2; Drug resistance in ERBB2 TMD/JMD mutants; Resistance of ERBB2 KD mutants to AEE788; Resistance of ERBB2 KD mutants to afatinib; Resistance of ERBB2 KD mutants to lapatinib; Resistance of ERBB2 KD mutants to neratinib; Resistance of ERBB2 KD mutants to osimertinib; Resistance of ERBB2 KD mutants to sapitinib; Resistance of ERBB2 KD mutants to tesevatinib; Resistance of ERBB2 KD mutants to trastuzumab; Signaling by ERBB2 ECD mutants; Signaling by ERBB2 KD Mutants; Signaling by ERBB2 TMD/JMD mutants
Signal Transduction: Downregulation of ERBB2 signaling; Drug-mediated inhibition of ERBB2 signaling; RHOBTB2 GTPase cycle; Signaling by ERBB2
Programmed Cell Death: Regulation of necroptotic cell death
Gene Ontology:
Molecular function: heat shock protein binding; kinase binding; protein binding; scaffold protein binding; protein-folding chaperone binding; Hsp90 protein binding; protein kinase binding; protein kinase regulator activity
Biological process: protein maturation; regulation of type I interferon-mediated signaling pathway; regulation of type II interferon-mediated signaling pathway; protein folding; protein stabilization; protein targeting; regulation of cyclin-dependent protein serine/threonine kinase activity; positive regulation of type 2 mitophagy; post-transcriptional regulation of gene expression
Cellular component: cytoplasm; cytosol; extracellular exosome; HSP90-CDC37 chaperone complex; protein folding chaperone complex
Genetic constraint (gnomAD): Loss-of-function variants: 9 observed, 48.97 expected, observed/expected ratio (o/e) 0.18, 90% interval 0.11 to 0.32. The upper end of that interval is the gene's LOEUF score, 0.32, which puts it in group 1 of 6, group 1 being the genes least tolerant of losing a copy. Missense variants: 388 observed, 532.76 expected, observed/expected ratio (o/e) 0.73, 90% interval 0.67 to 0.79. Synonymous variants: 193 observed, 198.02 expected, observed/expected ratio (o/e) 0.97, 90% interval 0.87 to 1.1.
Homologues: Orthologues: chimpanzee CDC37 (99% identical), dog CDC37 (97% identical), guinea pig CDC37 (97% identical), pig CDC37 (97% identical), mouse Cdc37 (95% identical), rat Cdc37 (95% identical), macaque CDC37 (92% identical), tropical clawed frog cdc37 (74% identical), zebrafish cdc37 (60% identical), Drosophila melanogaster Cdc37 (52% identical), Caenorhabditis elegans cdc-37 (39% identical), Caenorhabditis elegans K07E8.6 (18% identical). Paralogues in human: CDC37L1 (34% identical).
Diseases named in the same sentence as CDC37 in open-access papers:
CDC37 is named in the same sentence as 51 diseases in open-access papers, as found by Europe PMC text mining. Sharing a sentence is not in itself a finding about the gene and the disease. The quoted sentences say what the papers report.
breast cancer (13 papers, 2012 to 2025). A primary or metastatic malignant neoplasm involving the breast. "The observed immunostaining confirmed the cell surface localization of Cdc37 in both human breast cancer cell lines studied." (PMID 22912728, 2012). "In conclusion in the present work we demonstrate the cell surface localization of Cdc37 and its participation in invasion processes of breast cancer cells." (PMID 22912728, 2012). "The inhibition of MDA-MB-453 and MDA-MB-231 breast cancer cell motility, by the anti-Cdc37 antibody was shown using the wound healing assay." (PMID 22912728, 2012). "Our previous study reported that F806, could bind to the N-terminal of Hsp90 and inhibit Hsp90/Cdc37 interaction, resulting in the disassociation of Hsp90/Cdc37/client complexes and the degradation of Hsp90 client proteins in breast cancer cells." (PMID 25909284, 2015). "The Lnc712/HSP90/Cdc37 complex regulated cyclin-dependent kinase 2 (CDK2) activation and then triggered breast cancer cell proliferation." (PMID 31892853, 2020). "In order to examine the cell surface localization of Cdc37, unfixed MDA-MB-453 and MDA-MB-231 human breast cancer cells were incubated with the anti-Cdc37 antibody." (PMID 22912728, 2012). "Cell surface localization of Cdc37 was demonstrated by both immunocytochemistry on live MDA-MB-453 and MDA-MB-231 breast cancer cells and western blot using membrane fraction lysates derived from these cell lines." (PMID 22912728, 2012). "HER2 breast cancer (BC) cells often exhibit elevated expression of HER2, cell division cycle 37 protein (Cdc37), and Heat shock protein 90 (Hsp90), while the expression of Cullin5 (CUL5) is decreased." (PMID 39223632, 2024). "Here we report that Cdc37 is not restricted intracellularly but instead it is also present on the surface of MDA-MB-453 and MDA-MB-231 human breast cancer cells, where it is shown to participate in cancer cell motility processes." (PMID 22912728, 2012).
prostate carcinoma (9 papers, 2011 to 2024). A carcinoma that arises from epithelial cells of the prostate gland. "We have shown that SCAND1-MZF1(ZSCAN6) oligomerized complexes were bound to ‘an MZF1-binding site’ in chromatin in the CDC37 gene promoter region in prostate cancer cells." (PMID 36552758, 2022). "Consistently, we have shown that overexpressing SCAND1 and MZF1 form oligomers in chromatin and bind to an MZF1-binding site in the promoter region of CDC37 gene, and hetero-oligomers of SCAND1 and MZF1 can repress CDC37 gene expression in prostate cancer." (PMID 36552758, 2022). "We recently demonstrated that myeloid zinc finger 1 (MZF1) and SCAND1 reciprocally regulated CDC37 gene expression in prostate cancer." (PMID 32204513, 2020). "As expected, depletion of MZF1 in prostate cancer cells decreases CDC37 expression and reduces their tumorigenesis." (PMID 31963147, 2020). "Our data also indicated that CDC37 is crucial for the release of vesicular proteins and tumor progression in prostate cancer." (PMID 32204513, 2020). "CDC37 is particularly significant in prostate cancer as its overexpression leads to spontaneous prostate carcinogenesis in transgenic mice." (PMID 32204513, 2020). "Although there are several possible mechanisms for the elevation in CDC37 expression in prostate cancer, in the present study we focused on transcriptional regulation as the most immediate level of control." (PMID 31181782, 2019). "We showed that MZF1 binds to sites in the CDC37 promoter and strongly activates transcription; moreover, MZF1 expression is tightly correlated with CDC37 levels in clinical prostate cancer." (PMID 31181782, 2019). "Depletion of CDC37 reduced prostate cancer cell growth and attenuated the MEK-ERK signaling pathway and the PI3K-Akt signaling pathway." (PMID 31181782, 2019). "MZF1 became bound to these regulatory sites and trans-activated the CDC37 gene whereas MZF1 depletion decreased CDC37 transcription and reduced the tumorigenesis of prostate cancer cells." (PMID 31181782, 2019). "In conclusion, it was demonstrated that pro-oncogenic MZF1 and its potential antagonist SCAND1 coordinately regulate the expression of CDC37, a factor that is essential for prostate cancer tumorigenesis." (PMID 31181782, 2019). "We next examined MZF1 and CDC37 expression correlation with the prognosis of prostate cancer patients." (PMID 31181782, 2019). "CDC37 levels in the prostate cancer cells (PC-3, LNCaP, and DU-145) were higher than those of the normal cell line in confluent conditions." (PMID 31181782, 2019). "We first compared the expression levels of CDC37 between prostate cancer cell lines DU-145 and LNCaP, a castration-resistant prostate cancer (CRPC, also known as neuroendocrine prostate cancer (NEPC) cell line PC-3), and a normal prostate cell line (RWPE-1)." (PMID 31181782, 2019). "CDC37 is a crucial molecule in prostate cancer growth through its fostering of oncogenic kinases and our data strongly indicate that the chaperone is upregulated by MZF1." (PMID 31181782, 2019). "To investigate the potential clinical significance of MZF1 regulation of CDC37, we next examined the co-expression correlation of MZF1 and CDC37 in prostate cancer patient-derived tumor samples." (PMID 31181782, 2019). "CDC37 is particularly significant in prostate cancer as its overexpression leads to prostate carcinogenesis in transgenic mice." (PMID 31181782, 2019). "CDC37 levels in PC-3 cells were higher than those of the other prostate cancer cells and normal prostate cells in both confluent and growing conditions." (PMID 31181782, 2019). "Cdc37 has an increased level in proliferating tissues and organs and is highly expressed in certain tumors, such as prostate cancer." (PMID 29699578, 2018). "In prostate carcinoma, Cdc37 knockdown inactivated cell growth and sensitized tumors to Hsp90 inhibitors." (PMID 24278769, 2013).
prostate carcinoma (continued). "Cdc37 therefore seems to be a strong molecular candidate for targeted therapy, particularly in prostate carcinoma." (PMID 24278769, 2013). "Cdc37 levels are elevated in prostate cancer and pre-malignant prostatic neoplasias, Cdc37 overexpression in the prostate epithelium of transgenic mice having been found to result in a high incidence of hyperplasia." (PMID 27721330, 2011). "CDC37 has a critical role in progression of oral and prostate cancer." (PMID 39165691, 2024). "Indeed, SCAND1 represses the CDC37 gene (encoding cell division control 37) by interacting with MZF1 and suppressing prostate cancer progression." (PMID 36552758, 2022). "The expression of the cell division control 37 (CDC37) gene is increased in prostate cancer cells." (PMID 31963147, 2020). "High expression levels of MZF1 (p = 0.0287) and CDC37 (p = 0.0182) were correlated with poor prognosis of patients suffering from prostate cancer and showed a higher correlation than that of PSA (p = 0.154)—named after prostate-specific antigen—which is currently used for prostate cancer screening." (PMID 31181782, 2019). "Cdc37 appears to play a highly significant role in cancer and its forced expression in transgenic mice leads to prostatic hyperplasia and, when expressed in conjunction with the oncogene c-Myc, to prostate cancer." (PMID 24278769, 2013). "Notably, elevated expression of CDC37 was found in prostate cancer cells, although the regulatory mechanisms through which CDC37 expression becomes increased are unknown." (PMID 31181782, 2019). "We showed the molecular chaperones CDC37 and heat shock protein 90 (HSP90) and HSP90-rich exosomes to be crucial in promoting EMT in prostate cancer and tongue cancer and initiating EMT in normal epithelial cells." (PMID 36552758, 2022). "MZF1 has positive regulation on CDC37 gene transcription by binding the regulatory sites, while MZF1 deletion reduces CDC37 transcription and tumorigenicity of prostate cancer cells." (PMID 34732138, 2021). "Therefore, our data indicate that while MZF1 positively regulates CDC37, SCAND1 negatively regulates transcription, a finding which could be crucial in mechanisms of prostate cancer progression." (PMID 31181782, 2019). "The overexpressed MZF1 occupied genomic CDC37 promoter regions (−0.4k and −1.8k regions that contain MZF1-binding sites), further indicating that the CDC37 gene is regulated by MZF1 binding to these MZF1 binding sites in prostate cancer, as suggested by chromatin immunoprecipitation (ChIP) assay." (PMID 31181782, 2019). "However, Cdc37 knockdown inhibited growth of androgen receptor negative Prostate Carcinoma (PC-3 and DU-145) as effectively as it affected androgen-requiring LnCap cells." (PMID 24278769, 2013).
colorectal cancer (7 papers, 2007 to 2026). A primary or metastatic malignant neoplasm that affects the colon or rectum. "Cytosol HSP90 can interact with CDC37 to facilitate colorectal cancer progression." (PMID 33658487, 2021). "The currently most potent small molecule Hsp90/Cdc37 interface inhibitor, compound (18 h) (Kd = 0.5 μM) was more efficacious in reducing the growth of HCT116 cell-derived colorectal cancer xenografts than its predecessor, DDO-5936." (PMID 33672199, 2021). "This differential CDC37 assembly state likely reflects the different origins of the cell lines, as HCT116 is derived from colorectal carcinoma, while HEK293 is not of cancer origin." (PMID 39885126, 2025).
colon carcinoma (5 papers, 2008 to 2025). "Similarly, it also remains to be determined how HSP90 interacts with Akt in mutant BRAF colon cancer cells deficient in CDC37." (PMID 27391062, 2016). "The effect of CDC37 on Akt phosphorylation, similar to its stabilizing effect on Akt, appears to be specific to colon cancer cells with activating mutations in BRAF, suggesting that mutant BRAF has reprogrammed the signaling network of protein kinases in colon cancer cells." (PMID 27391062, 2016). "Although how CDC37 acts differently on Akt in mutant and wild-type BRAF colon cancer cells remains unknown, it is unlikely caused by mutations in its gene as all the colon cancer cell lines included in this study harbored wild-type CDC37." (PMID 27391062, 2016). "The combined inhibition of Hsp90 and CDC37 was efficient in abrogating the phosphorylation of Akt in mutant BRAF colon cancer cells." (PMID 36012578, 2022). "Consistent with inhibition of reactivation of Akt and ERK, CDC37 knockdown sensitized mutant BRAF colon cancer cells to AUY922-induced apoptosis." (PMID 27391062, 2016). "Our results suggest that CDC37 is a potential therapeutic target in the treatment of mutant BRAF colon cancers, in particular, in combination with HSP90 inhibitors." (PMID 27391062, 2016). "Regardless, our results clearly demonstrated that CDC37 plays an essential for rebound activation of Akt in mutant BRAF colon cancer cells after treatment with AUY922." (PMID 27391062, 2016). "In the absence of a change in the expression levels of Akt, these results indicate that CDC37 plays an important role in phosphorylation of Akt in mutant BRAF colon cancer cells." (PMID 27391062, 2016). "In support, CDC37 was co-precipitated with Akt in mutant BRAF colon cancer cells in the presence of AUY922, whereas HSP90 was similarly co-precipitated with Akt in these cells when CDC37 was knocked down." (PMID 27391062, 2016). "Strikingly, siRNA knockdown of CDC37 not only inhibited rebound activation of Akt in mutant BRAF colon cancer cells after treatment with AUY922, but also reduced the basal levels of activation of Akt in these cells." (PMID 27391062, 2016). "As in yeast, transfected HCT116 human colon carcinoma cells overexpressing PP5 showed a marked decrease in pSer13-Cdc37 levels detected in cell lysates compared with vehicle-transfected cells, but with no decrease in total Cdc37." (PMID 18922470, 2008). "Stabilization of Akt in mutant BRAF colon cancer requires both Hsp90 and CDC37." (PMID 36012578, 2022). "Importantly, all the colon cancer cell lines included in this study harboured wild-type CDC37 as demonstrated by sequencing of all the 8 exons (including the intron/exon boundaries) of the gene." (PMID 27391062, 2016). "Since CDC37 interacts with protein kinases and can stabilize and activate clients in concert with HSP90 or independently of HSP90, we investigated whether CDC37 is involved in reactivation of Akt in mutant BRAF colon cancer cells treated with AUY922." (PMID 27391062, 2016). "In addition, we demonstrate that reactivation of ERK is due to incomplete degradation of mutant BRAF by AUY922, whereas reactivation of Akt is triggered by the activity of CDC37 in mutant BRAF colon cancer cells." (PMID 27391062, 2016). "In addition, AUY922 triggered killing of mutant BRAF colon cancer cells with CDC37 knocked down in 3-dimensional cultures." (PMID 27391062, 2016). "Moreover, it is not related to differences in the expression of the protein, in that CDC37 was expressed at comparable levels between colon cancer cell lines carrying wild-type BRAF and whose with mutant BRAF." (PMID 27391062, 2016). "Whether CDC37 has comparable effects on other kinases in mutant BRAF colon cancer cells and whether it has similar effects on other types of cells carrying mutations in BRAF needs further investigation." (PMID 27391062, 2016).
colon carcinoma (continued). "In addition, we have shown that rebound activation of ERK and Akt caused respectively by the persistent expression of mutant BRAF and the activity of CDC37 is responsible for resistance of mutant BRAF colon cancer cells to AUY922." (PMID 27391062, 2016). "Intriguingly, our results showed that knockdown of CDC37 caused a moderate decrease in the basal levels of ERK activation and reactivation of ERK after treatment with AUY922, suggesting that CDC37 is able to stabilize mutant BRAF independently of HSP90 in colon cancer cells." (PMID 27391062, 2016). "However, it is intriguing that neither inhibition of HSP90 by AUY922 nor knockdown of CDC37 caused reduction in the expression of Akt that is a client of HSP90 in mutant BRAF colon cancer cells." (PMID 27391062, 2016). "Similar results were observed in the activating KRAS-mutant colon cancer cell line HCT116, where braftide reduced the CDC37–RAF interaction at lower doses than in HEK293 cells, suggesting this effect is not cell line specific." (PMID 41371342, 2025). "Intriguingly, siRNA knockdown of CDC37 also reduced the basal levels of ERK activation, and inhibited its reactivation, albeit moderately, in mutant BRAF colon cancer cells after treatment with AUY922." (PMID 27391062, 2016). "Nevertheless, it did not affect the expression of Akt in mutant BRAF colon cancer cells, suggesting that CDC37 is not essential for chaperoning Akt in the cells." (PMID 27391062, 2016). "Nevertheless, CDC37 did not appear to play a role in wild-type BRAF colon cancer cells, in that AUY922 alone inhibited Akt expression in the cells." (PMID 27391062, 2016). "Moreover, CDC37 was expressed at comparable levels, which were not affected by treatment with AUY922, in the colon cancer cell lines irrespective of their mutational status of BRAF." (PMID 27391062, 2016). "An important finding of this study was that CDC37 knockdown not only blocked rebound activation of Akt in mutant BRAF colon cancer cells after treatment with AUY922, but also inhibited constitutive activation of Akt in mutant but not wild-type BRAF colon cancer cells." (PMID 27391062, 2016).
pancreatic cancer (5 papers, 2015 to 2022). "Indeed, the Hsp90/Cdc37 inhibitors celastrol, (−)-epigallocatechin-3-gallate (EGCG, identified also in this study), and withaferin A were previously successfully tested against pancreatic cancer cell growth in vitro and in vivo by the Sun group." (PMID 33672199, 2021).
melanoma (4 papers, 2019 to 2024). A malignant, usually aggressive tumor composed of atypical, neoplastic melanocytes. "Another gene is CDC37, which is observed to be an essential gene to maintain the role of proteins that interact with protein kinases in melanoma." (PMID 31673075, 2019). "Interestingly, the PI3K-Akt signaling pathway shared all genes enriched in melanoma pathway (e.g., CDK6, FGF20, and MITF) and included three additional genes (i.e., RPTOR, COMP, and CDC37), suggesting a higher level of significance and potential relevance." (PMID 37829282, 2023).